MMP2 (matrix metallopeptidase 2)
Diseases named in the same sentence as MMP2 in open-access papers (continued):
Sharing a sentence is not in itself a finding about the gene and the disease.
tumor (continued). "Matrix metalloproteinase-2 (MMP-2) and MMP-9 cleavage by SCUBE3 releases fragments, which can bind to transforming growth factor-b (TGF-b) type II receptors, thereby activating the TGF-b signal transduction and promoting tumor development." (PMID 35663937, 2022). "By controlling the BCL2, BAX, cleaved caspase-3, MMP-2, and MMP-9 pathways, the results showed the potential of brusatol delivered by plCSA-modified NPs as a chemotherapeutic agent for the targeted therapy of tumours." (PMID 36559281, 2022). "Here, we developed MMP‐2‐sensitive FTH1 NCs—specifically TmSm‐modified FTH1 NCs carrying YM155 (FTS/YM155 NCs)—for the codelivery of YM155 and TmSm to synergistically inhibit survivin activity at both the transcript and protein levels at a tumor‐specific site." (PMID 35600646, 2022). "KNTC1 has been speculated to facilitate tumor cell migration and invasion by regulating MMP9 and MMP2." (PMID 35389773, 2022). "MMP2 and MMP9 are considered to exert an important role in tumor metastasis." (PMID 35912155, 2022). "MMP-2-sheddable PGDA7 and the MMP-2-insensitive PDA7 analogue NPs were administered via intravenous (i.v.)injection at an identical ARV771 dose of 10 mg/kg and PPa dose of 5.0 mg/kg when the tumour volume reached 200 mm3." (PMID 35882867, 2022). "Therefore, we assessed the effect of cordycepin on the expression of EMT-related proteins (N-cadherin, E-cadherin, snail, and ZEB1) and matrix metalloproteinases (MMP2 and MMP9) in tumor tissues by immunohistochemistry and Western blotting." (PMID 36142286, 2022). "Last but not least, in obese patients, adipocytes participate in “tumour niche” establishment by synthesis of MMPs, especially MMP2 and MMP9, that mediate the remodelling of tumour extracellular matrix, thus promoting motility and invasion of melanoma cells." (PMID 35334544, 2022). "Besides, the suppressive role of hsa_circ_0004396 knockdown on cell migration and invasion in tumor cells was partially restored using miR‐615‐5p reduction or PAK1 elevation, as evidenced by decreased MMP‐2 level." (PMID 35500159, 2022). "MMP2 and MMP9 are confirmed as crucial regulators of tumor metastasis." (PMID 35030977, 2022). "Interestingly, the previous study performed on sarcoids confirmed the significant over-expression of both MMP2 and MMP9 genes in the tumor tissue and in cell lines transfected with BPV-1 gene construct." (PMID 35742950, 2022). "MMP-2 and MMP-9 are the most well-studied and major promoters of tumor cell invasion." (PMID 35204054, 2022). "Moreover, LYN, MMP2, PRKCQ, and TLR1 can affect SKCM by influencing tumor cell metastasis, UV-induced cell injury, the NF-κB signaling pathway, and apoptosis." (PMID 36171883, 2022). "Subsequently, western blot showed that the expression levels of E-cadherin and HO-1 were notably enhanced by Lut or erastin, whereas MMP2, vimentin, GPX4, and SLC7A11 expression levels in tumor tissues treated with Lut or erastin were remarkably inhibited compared with those in the controls." (PMID 35656025, 2022). "IL-6 also promotes the angiogenesis and metastasis that contribute to the expression of matrix metalloproteinase 2 (MMP-2), expression of VEGF and bFGF by tumor cells and also favor metastasis events by attracting metastatic cells outside the primary site of the tumor." (PMID 36172343, 2022). "MMP2 and MMP14, affecting the top enriched biological functions, were mainly expressed in iCAFs and can promote extracellular matrix degradation and tumour cell invasion." (PMID 35184420, 2022). "TGF-β2, expressed by GAMs, induces MMP2 expression and blocks TIMP-2, promoting tumor invasion." (PMID 35448036, 2022). "Our particular interest lies in the roles MMP-2 and MT1-MMP serve within the nucleus, as they may provide critical insights into cancer epigenetics and tumor migration and invasion." (PMID 36076910, 2022). "Previous study has shown that MMP-2 and MMP-9 play important roles in tumor invasion and migration." (PMID 35220896, 2022).
tumor (continued). "HA-AuNR/M-M2pep showed better accumulation at tumor sites and discharged M2-pep in the TME with high MMP2 expression to specifically eliminate M2-like TAMs, which induced ICD to efficiently suppress tumor growth and prolong the survival of melanoma-bearing animals." (PMID 35183252, 2022). "Consistent with this hypothesis, it has been shown that the expression of several proangiogenic factors, such as VEGF, MMP2, MMP9 and HIF-1α, which are highly upregulated in IHs during the proliferative phase, decrease after tumor involution." (PMID 35563552, 2022). "Importantly, deflamin was effective in inhibiting MMP-2, MMP-9, and general ECM remodeling, favoring spatial constraints of tumor growth/progression and limited nutrient/oxygen supply, due to decreased angiogenesis." (PMID 36551666, 2022). "MMP-9 and MMP-2 belong to gelatinase, and they are the pivotal hydrolytic enzymes involved in hydrolyzing type IV collagen, a central constituent of the ECM and promoted tumor metastasis." (PMID 35954126, 2022). "MMPs, especially MMP-9 and MMP-2, can digest the ECM and facilitate the metastasis of tumor cells." (PMID 35954126, 2022). "MMP-2 and MMP-9 are most closely related to tumor invasion and metastasis." (PMID 36142286, 2022). "MMP2-cleavable peptide (GPLGIAGQ) was employed to initiate the de-shielding of liposomal carriers from PEG, resulting in increased cellular internalization and enhanced drug distribution in the tumor area." (PMID 36104946, 2022). "Moreover, gelatine zymography confirmed the expression of pro-active MMP-2 (9/9) and MMP-9 (9/9) and, most importantly, indicated the presence and increased activity of their active forms (82 and 62 kDa, respectively) in tumour samples." (PMID 36518899, 2022). "MMP is an extracellular matrix degradation enzyme whose main members MMP-2 and MMP-9 are the most critical proteins involved in tumor cell invasion, so the increased expression of MMPs may increase the invasion and metastasis of malignancies." (PMID 36225172, 2022). "In the tumour cells, cabozantinib interrupts VEGFR1/VEGFR2/c-KIT/TIE2 pathways, downregulating angiogenic factors (HIF1α, VEGFA) and vascular remodelling factors (MMP2, MMP9)." (PMID 35106125, 2022). "Likewise, injection of ApoSQ inhibited the activation of migration- and invasion-related signaling pathways, including the Smad2/3, FAK, ERK, and Akt pathways, as well as the protein expression of MMP2 and MMP12 in CD326+ tumor cells." (PMID 36241874, 2022). "In brief, MMP-2 and MMP-9 proteins are two crucial facilitators that are conducive to potentiating tumor metastatic and invasive potentials, these therapeutic candidate agents are expected to be used to the clinic CRC treatment and intervention by targeting the two crucial targets." (PMID 35308223, 2022). "High expression of MMP-2 in the TME resulted in the cleavage of peptide one on AuNPs@Pep1/Pep2, consequently the activation of peptide two resulting in the self-aggregation of AuNPs at tumor sites." (PMID 36230480, 2022). "HMGB1 and its subsequent binding to RAGE can trigger the production of proinflammatory cytokines through NF-kB activation, as well as the expression of pro-invasive and proteolytic matrix metalloproteinases (MMPs), such as MMP2 and MMP9, leading to tumor invasion and metastasis." (PMID 35727208, 2022). "Moreover, CD147 acts as a key role in mediating tumor cell invasiveness via regulating MMP expression, such as MMP-2 and MMP-9 in adjacent cancer cells or CAFs." (PMID 35464411, 2022). "In addition, B7-H3 induces tumor cell EMT processes by downregulating e-cadherin and upregulating MMP-2/-9 expression." (PMID 36741734, 2022). "The ENT-loaded LyP-1-modified nanosystem provided enhanced anti-tumor activity against KYSE-30 cells with direct targeting of tumor lymphatics, triggered nucleus rupture, mitochondrial degradation, decreased cell proliferation and migration, as well as restricted VEGF-C and MMP2 expression." (PMID 35337150, 2022).
tumor (continued). "STAT3 is known to activate matrix metalloproteinase 2/9 (MMP2/9) gene expression, which could mediate an enhancement effect on tumor invasiveness." (PMID 35463323, 2022). "Evidence from oncology studies suggests that activation of the MAPK/Erk signaling pathway could elevate the expression of MMP-2 and MMP-9 in different tumor cells, thereby enhancing their proliferation and invasion and metastasis." (PMID 36345403, 2022). "In non-small-cell lung cancer cell lines, lncRNA PVT1 can bind to miR-424-5p to decrease the expression of factors in tumor progression, such as CRAM, MMP-2, MMP-9 and Bcl2, to inhibit growth and increase the expression of Bax, thus suppressing the development of tumor cells." (PMID 35409396, 2022). "When the lipid-polymer hybrid nanoparticles enter the tumor tissue by EPR effects, the lipid layer is degraded by the overexpressed MMP-2 and the platelet antibody and dox-loaded inner core are released to mediate effects at different regions of the tumor microenvironment." (PMID 35845404, 2022). "Besides, matrix metalloproteinases (MMPs), especially MMP-2 and MMP-9, are highly expressed in a variety of tumor tissues and play an important role in the development of tumors." (PMID 35979035, 2022). "MMP-2 (Gelatinase A), the TME’s most prevalent MMP promotes tumor invasion." (PMID 36275750, 2022). "In addition, α2β1 integrin was shown to promote OC cell invasion by increasing matrix metalloproteinase (MMP)-2/MMP-9 activation, thereby disaggregating tumor cell spheroids and enhancing cell proliferation." (PMID 34689222, 2022). "We, therefore, measured the gelatinases MMP2 and MMP9 in tumour tissue and supernatants from BMDM." (PMID 33758004, 2022). "Matrix metalloproteinase 2 (MMP-2) contributes to angiogenesis and tumor invasion." (PMID 35216384, 2022). "Furthermore, integrin α6β1-dependent platelet-tumor cell interaction promotes the release of platelet granules and increases the expression of MMP-1 and MMP-2 in CTCs, favoring the extravasation of tumor cells." (PMID 35936717, 2022). "Our results show that MMP-2, -7, -9, and -13 are mainly expressed by immune cells and hepatocytes, and no tumor cells were positive for MMP-9 or -13." (PMID 35884455, 2022). "MMP2 and MMP9 are two of the main members of the MMP family that can downregulate the expression of E-cadherin and regulate the cleavage of E-cadherin to produce extracellular fragments, which are essential for tumor metastasis." (PMID 35770085, 2022). "In HT-1080 tumor cells, progesterone-induced blocking factor (PIBF) treatment increases STAT6 phosphorylation, and inhibition of PIBF with siRNA significantly reduces MMP2 expression." (PMID 35600336, 2022). "The enzyme activities of MMP-2 and MMP-9 in the plasma of the tumor control group were set at 100%." (PMID 35711540, 2022). "MMP-2 and MMP-9, also known as gelatinases, have been long recognized as major contributors to the proteolytic degradation of ECM during tumor invasion, which are responsible for mediating the degradation of different components of the ECM, the shackle for tumor." (PMID 35929837, 2022). "The increased expression of TNF-α, TGF-β, MMP-2, and MMP-9 might explain how the P. gingivalis LPS exerts pro-tumor effects." (PMID 36552854, 2022). "Analysis of bulk tumour mRNA displayed a strong correlation between ACTA2, a marker of MSCs, and matrix remodelling enzymes (MMP2), ECM proteins (VCAN, FN1, COL1A1), immunomodulatory molecules (Serpine1, CXCL12), innate immune cell markers (CD14, ITGAX) and adaptive immune cell markers (CD4)." (PMID 34885111, 2021). "Nuclear import of HIF-1A as a transcription factor is a hallmark event in HIF-1 dependant hundreds of target gene activation, such as angiogenic gene including VEGF-A, Flt-1, ang-1, MMP-2 and MMP-9 which promotes tumour angiogenesis, metastasis and clinical prognosis." (PMID 33403040, 2021).
tumor (continued). "Recently, a study showed that Lut inhibits the metastasis of ovarian cancer cells (A2780 cells) by downregulating the expression of MMP-2 and MMP-9 both in vitro (A2780 cells) and in vivo in a tumor model comprising subcutaneous injection of A2780 cells in nude mice." (PMID 33498927, 2021). "Finally, performed qRT-PCR and western blot analysis in Lnc-408-engineered BC cells, we confirmed that MMP2, ITGB1, and COL1A1 exhibited significant and substantial changes in Hs578T, MCF-7 cells, and primary BC tumor cells." (PMID 34079084, 2021). "In addition, a MMP-2 cleavable peptide was introduced into the DNA-5, which endowed the UCNP nanocages with tumor-responsive gene release properties." (PMID 34427999, 2021). "Secreted CSF1 increases MMP2 and VEGF-A expression in TAMs, promoting tumor angiogenesis." (PMID 33406733, 2021). "MMP2 is an important player in HPV+ OPSCC, where it promotes tumor cell migration and invasion." (PMID 34684173, 2021). "Moreover, in the morphologically normal tissue adjacent to the tumor, significant expression of MMP-1, MMP-2, and MMP-9 was found, which additionally contributes to an increase in the destructive potential of the tumor." (PMID 34830452, 2021). "For example, miRNA-199a-3p weakened tumor progression in HCC by targeting VEGFA, HGF, or MMP2." (PMID 34876904, 2021). "MMP2 also activates TGF-β to promote epithelial-mesenchymal transformation (EMT), while by releasing vascular endothelial growth factor (VEGF), MMP9 promotes tumor angiogenesis." (PMID 34595119, 2021). "Furthermore, PBMF treatment notably upregulated the mRNA expression levels of GSK-3β, E-cadherin, Bax, Caspase-3, and Caspase-9 but substantially downregulated those of β-catenin, N-cadherin, MMP-2, MMP-9, Snail, and Cyclin D1 in tumor tissues." (PMID 33964908, 2021). "In addition, the expression of invasive factors matrix metalloproteinase-2 and 9 (MMP2, MMP9) was increased in ascitic cells compared to cells from primary tumours." (PMID 34211089, 2021). "Our current findings are in line with the available reports wherein in vitro/in vivo models have shown that chrysin inhibits tumor metastasis by decreasing the expression of MMP9 and MMP2 as well as COX-2 and i-NOS, and modulates the PI3K/AKT signaling pathway." (PMID 35096000, 2021). "Then, 27 studies were excluded as they detected MMP2/MMP9 expression in serum (n = 17) or cytosol tumor extracts (n = 1) or in stromal cells (n = 1), investigated mRNA expression (n = 4), duplicated with others (n = 4)." (PMID 33568081, 2021). "In an opposite manner, mRNA levels of some EMT markers such as Mmp2, Cdh2, and Acta2 are virtually absent in the ascites tumor cells." (PMID 34737944, 2021). "In another study, MMP-2 increased cell proliferation and reduced apoptosis in OVCAR3 (ovarian cancer cell line) cells, thereby lowering the effect of chemotherapeutic drugs on tumor cells." (PMID 35145899, 2021). "Altogether, they indicate that Mmp2 signals through both BATF3+ DCs and T cells to enhance tumor growth, and in the absence of Mmp2, this dependency is lost." (PMID 34032639, 2021). "After therapeutic period, Andro could remarkably reduce IL-6, IL-1β, TNF-α, VEGF, MMP-2 level in blood and IL-10, TGF-β, NF-κB level of tumor tissue with significantly statistical implications (p < 0.01)." (PMID 33967748, 2021). "A positive correlation was found between the MMP‐2 and IGF‐1R expression in OSCC tumours." (PMID 34528373, 2021). "Additionally, the upregulation of PAR-2 promotes matrix metalloproteinase-2 (MMP-2) and MMP-9, both of which play a key role in the metastasis of tumor cells." (PMID 34068970, 2021). "In the same model, an ATX-enriched diet (15 mg/kg) suppressed tumor progression via inhibition of the JAK/STAT3 signaling pathway and its downstream targets cyclin D1, MMP-2 and -9, and VEGF, preventing cell proliferation and invasion and, consequently, regulating tumor microvascular density." (PMID 34677429, 2021).
tumor (continued). "Our study details the mechanism by which hypoxemia upmodulates the extracellular release of PSPC1 by means of MMP2, such that plasma PSPC1 together with TGFβ activation signaling further promotes tumor metastasis and supports cancer aggressiveness in patients with OSA." (PMID 34359789, 2021). "Of note, MMP2 and MMP3 also acted as tumor promoters in five out of eight cases." (PMID 33450808, 2021). "On the other hand, decreased methylation of tumor-related genes such as PPAR-gamma, E-cadherin, matrix metalloproteinase-2 (MMP2), cyclooxygenase-2 (COX-2) or phosphatase and tensin homolog deletion on chromosome 10 (PTEN) was observed after PUFAs treatment of CRC cells." (PMID 34371938, 2021). "On one hand, FAK mediates the phosphorylation of Paxillin at local adhesion sites, thereby regulating focal adhesion, increasing tumor cell fluidity, and contributing to VM development; on the other hand, FAK regulates MMP-2 and MT1-MMP activities through Erk1/2, thereby promoting ECM remodeling." (PMID 33397409, 2021). "MMP2 and MMP9 degrade type IV collagen in basement membranes, increasing tumor aggressiveness." (PMID 34830271, 2021). "Claudin-1 showed a trend to elevation in the tumor tissues of C150-treated mice but the change was not statistically significant, whereas the pro-metastasis marker MMP-2 trended to decrease with C150 treatment." (PMID 34976816, 2021). "Moreover, the secretion of MMP-2 and MMP-9 is significantly inhibited, thereby inhibiting the migration and invasion of tumour cells." (PMID 34539401, 2021). "Therefore, inhibiting the expression of MMP-2, MMP-9, and MMP-1 is important to prevent tumor invasion and metastasis." (PMID 33833342, 2021). "BATF3 cDC1s (CD8α+ in lymphoid tissues and CD103+ in nonlymphoid ones) were key in mediating MMP2 activity in tumors, as, in their absence, Mmp2-OE tumor growth was reduced." (PMID 34032639, 2021). "TGF-β also enhances tumor invasiveness and angiogenesis by promoting the production and secretion of matrix metalloproteases proteinase-2 (MMP-2) and matrix metalloproteinase-2 (MMP-9) and downregulating the expression of tissue inhibitors of metalloproteases (TIMP)." (PMID 34335834, 2021). "The important members, including MMP-2 and MMP-9, mainly work to decompose collagen IV in the basement membrane, break the tight and ordered junction between cells, and thereby contributing to tumor growth and metastasis." (PMID 34587874, 2021). "In addition, HSD17B6 overexpression suppressed the expression of MMP2 and MMP9, which are critical proteinases for tumor invasion and metastasis through degrading extracellular matrix and vascular basement membrane." (PMID 34750355, 2021). "Therefore, MMP-2 and MMP-9 are considered as potential biomarkers for the process of tumor development and are important potential targets for antitumor therapy." (PMID 33959183, 2021). "Among them, MMP-1, MMP-2, and MMP-9 are closely related to tumor invasion and metastasis." (PMID 35280249, 2021). "Plasmin mediates MMP2 activation and ECM degradation favoring tumor invasion." (PMID 34690699, 2021). "This micellar nanoplatform was constructed by an MMP2-sensitive copolymer (PEG-pp-PEI-PE) via self-assembly, which displayed exceptional stability, efficient siRNA condensation by PEI, PTX solubilization in the lipid core, and tumor targeting via both the EPR effect and MMP2 sensitivity." (PMID 34249894, 2021). "Western blot result revealed that oe-ADAMTS9-AS1 markedly decreased the expression of tumor markers for proliferation and invasion, such as Ki67, PCNA, MMP-2, MMP-9, suggesting that oe-ADAMTS9-AS1 could reduce tumor proliferative, and invasive abilities." (PMID 34900984, 2021). "The active MMP7 can also cleave the pro-MMP2 and pro-MMP9 to facilitate tumor invasion." (PMID 33936204, 2021). "Overexpression of MMP2 and MMP9 favour tumour recurrence in patients with stage T1 BC." (PMID 34142438, 2021).